SENP7 (SUMO specific peptidase 7)
Description:
Protease that acts as a positive regulator of the cGAS-STING pathway by catalyzing desumoylation of CGAS. Desumoylation of CGAS promotes DNA-binding activity of CGAS, subsequent oligomerization and activation (By similarity). Deconjugates SUMO2 and SUMO3 from targeted proteins, but not SUMO1. Catalyzes the deconjugation of poly-SUMO2 and poly-SUMO3 chains. Has very low efficiency in processing full-length SUMO proteins to their mature forms.
Tractability: Small molecule: a structure with a bound ligand is known; it belongs to a druggable protein family. PROTAC: ubiquitination databases record sites on it; its protein half-life has been measured; a small molecule that binds it is known.
Target class: Protease; Enzyme; Cysteine protease CE clan; Cysteine protease C48 family; Cysteine protease
Gene: Protein-coding gene on chromosome 3 (101,324,205 to 101,513,241, reverse strand). Ensembl gene ENSG00000138468.
Subcellular location: Cytoplasm
Subcellular location (Human Protein Atlas): Nucleoplasm; Centrosome; Cytosol; Nuclear bodies
Gene Ontology:
Molecular function: protein binding; SUMO-specific endopeptidase activity; cysteine-type peptidase activity
Biological process: antiviral innate immune response; protein desumoylation; proteolysis
Cellular component: nucleoplasm; nucleus; cytoplasm; postsynaptic cytosol; presynaptic cytosol
Genetic constraint (gnomAD): Loss-of-function variants: 22 observed, 62.4 expected, observed/expected ratio (o/e) 0.35, 90% interval 0.25 to 0.5. The upper end of that interval is the gene's LOEUF score, 0.5, which puts it in group 2 of 6, group 1 being the genes least tolerant of losing a copy. Missense variants: 601 observed, 738.7 expected, observed/expected ratio (o/e) 0.81, 90% interval 0.76 to 0.87. Synonymous variants: 230 observed, 267.89 expected, observed/expected ratio (o/e) 0.86, 90% interval 0.77 to 0.96.
Homologues: Orthologues: chimpanzee SENP7 (99% identical), macaque SENP7 (96% identical), dog SENP7 (85% identical), pig SENP7 (84% identical), rabbit SENP7 (77% identical), guinea pig SENP7 (75% identical), mouse Senp7 (70% identical), tropical clawed frog senp7 (34% identical), zebrafish si:dkey-100n23.3 (25% identical), zebrafish senp7b (22% identical), Drosophila melanogaster pira (15% identical), Caenorhabditis elegans ulp-4 (7% identical). Paralogues in human: SENP6 (25% identical).
Diseases named in the same sentence as SENP7 in open-access papers:
SENP7 is named in the same sentence as 39 diseases in open-access papers, as found by Europe PMC text mining. Sharing a sentence is not in itself a finding about the gene and the disease. The quoted sentences say what the papers report.
breast carcinoma (2 papers, 2019 to 2024). "The long SENP7 transcript has been reported to promote epithelial–mesenchymal transition and decrease the cell adhesion molecule E-cadherin (CDH1) in breast cancer cell line, which could lead to the metastasis of the disease." (PMID 31318878, 2019). "Two of them, PATL1 and PRRC2B were discussed earlier; SENP7 is a marker of poor prognosis in colon cancer; SPAG9 is expressed in a variety of malignancies and regulated by QKI in lung cancer; UBR5 promotes postsurgical breast cancer lung metastases, and NSD1 exerts tumor suppressive functions." (PMID 39664813, 2024).
colon cancer (2 papers, 2022 to 2024). "Since CD8+ T cells play a crucial role in cell-mediated tumor killing, we inoculated WT and KO mice with MC38 murine colon cancer cells to determine whether SENP7 is required for antitumor T cell immune responses in vivo." (PMID 35143421, 2022).
colorectal cancer (2 papers, 2022 to 2026). A primary or metastatic malignant neoplasm that affects the colon or rectum. "To elucidate the role of SENP7 in the tumour microenvironment (TME) of colorectal cancer CRC, we further employed an in situ tumour model in which adoptive transfer of B cells overexpressing SENP7 significantly accelerated tumour growth." (PMID 41362746, 2026). "To investigate the expression profile of SENP7 in tumor-infiltrating T cells, we isolated CD4+ T cells and CD8+ T cells from patient-derived colorectal cancer (CRC) tissue for immunoblot analysis." (PMID 35143421, 2022). "Importantly, lowering T cell–intrinsic ROS restricted SENP7 cytosolic translocation and repressed CD8+ T cell metabolic and functional activity in human colorectal cancer samples." (PMID 35143421, 2022).
inflammatory bowel disease (2 papers, 2020 to 2022). A spectrum of small and large bowel inflammatory diseases of unknown etiology. "Although SENP7 has been reported to potentiate cGAS activation and contribute to the expansion of proinflammatory γδT cells in inflammatory bowel disease, the related studies used an in vivo model of SENP7 knockdown." (PMID 35143421, 2022). "Lower sumoylation rates, possibly due to enhanced SENP7 desumoylase activity, were also detected in patients with inflammatory bowel disease and were described as a prerequisite for the onset of inflammation in colons from mice with dextran sodium sulfate- (DSS-) induced colitis." (PMID 32948837, 2020).
lung carcinoma (2 papers, 2020 to 2024). "In contrast, blood cell traits and hematological diseases were implicated with a wider range of loci, including TERC, TERT, SENP7, ATM, BBOF1, and MROH8; this result is similar to those for the respiratory function and lung cancers that also involved multiple TL loci." (PMID 32109421, 2020).
oral squamous cell carcinoma (2 papers, 2021 to 2022). "In fact, expression of NF-κB has been reported in the saliva of canine LOM and oral squamous cell carcinoma, and the expression of sentrin/small ubiquitin-like modifier-specific protease 7 (SENP7) has been reported in saliva of dogs with oral squamous cell carcinoma." (PMID 34411146, 2021). "One of the identified proteins was sentrin-specific protease 7 (SENP7), the expression of which significantly increased in oral squamous cell carcinoma." (PMID 36077913, 2022).
autoimmune disease (1 paper, 2017). A disorder resulting from loss of function or tissue destruction of an organ or multiple organs, arising from humoral or cellular immune responses of the individual to their own tissue constituents. "Interestingly, we observed that SENP7 was significantly up-regulated in patients with autoimmune disease, indicating that SENP7 might synergize the action of cGAS in the pathogenesis of certain autoimmune disorders." (PMID 28095500, 2017).
Autoimmunity (1 paper, 2017). The occurrence of an immune reaction against the organism's own cells or tissues. "Future investigation will focus on generating the SENP7 conditional knockout mice and analyzing its potential immunoregulatory function in autoimmunity and cancer immunology." (PMID 28095500, 2017).
cataract (1 paper, 2020). Partial or complete opacity of the crystalline lens of one or both eyes that decreases visual acuity and eventually results in blindness. "Also, male cataract patients had higher levels of SENP3, SENP7, and SENP8 than female patients." (PMID 32827359, 2020).
Insulin resistance (1 paper, 2024). Increased resistance towards insulin, that is, diminished effectiveness of insulin in reducing blood glucose levels. "However, Senp7 KO and AKO mice did not develop insulin resistance or fatty liver." (PMID 38677512, 2024).
lipodystrophy (1 paper, 2024). A congenital or acquired disorder characterized by abnormal loss or redistribution of the adipose tissue in the body. "Senp7-deficient mice displayed a lack of WAT, which is closely related to lipodystrophy." (PMID 38677512, 2024).
lymphoma (1 paper, 2022). A malignant (clonal) proliferation of B- lymphocytes or T- lymphocytes which involves the lymph nodes, bone marrow and/or extranodal sites. "Moreover, our results suggest that the suppression or inactivation of the related SENP7 contributes to the hyperSUMOylation phenotype in MYC-driven lymphomas." (PMID 35022408, 2022). "Notably, Senp7 transcript level was suppressed during lymphomagenesis and SENP7 protein was absent in Eμ-myc lymphomas." (PMID 35022408, 2022).
oral cancers (1 paper, 2019).
partial lipodystrophy (1 paper, 2024). Loss and redistribution of subcutaneous and/or visceral adipose tissue from specific regions of the body. "This might be related to the relatively mild WAT loss in Senp7-deficient mice, which is consistent with the clinical characteristics of asymptomatic partial lipodystrophy patients." (PMID 38677512, 2024).
prostate tumor (1 paper, 2022). "Furthermore, when comparing prostate tumor specimens with SPOP mutations to those with wild-type SPOP, SENP7 is expressed at higher levels, and SENP7 depletion causes PCa cells to become senescent." (PMID 35887358, 2022).
Werner syndrome (1 paper, 2020). "We further characterized SENP7 target CpGs by overlapping the CpGs with trait-related probes and found an enrichment for Werner syndrome-associated CpGs." (PMID 32859263, 2020). "Interestingly, the Werner syndrome gene product is modified by SUMO and may therefore be related to SENP7’s function as SUMO protease." (PMID 32859263, 2020).
tumor (14 papers, 2009 to 2026). "Depletion of CD8+ T cells eliminated the inhibitory effect of SENP7-deficient B cells on tumour progression." (PMID 41362746, 2026). "We have previously implicated SENP7 in promoting cell survival after harmful OGD in tumor cells, showing an opposite effect to the SENP3 protease promoting cell death." (PMID 40348773, 2025). "Cell proliferation–related genes, including Mki67, Cdk1, Plk1, and Ccnb1, were downregulated in tumor-infiltrating SENP7-deficient CD8+ T cells." (PMID 35143421, 2022). "Intriguingly, the phosphoinositide 3-kinase/mTOR (PI3K/mTOR) signaling pathway–related gene expression profile was altered in tumor-infiltrating SENP7-deficient CD8+ T cells." (PMID 35143421, 2022). "Our findings revealed that both elevated and reduced expression levels of UBC9, SENP1, SENP3, SENP5, and SENP7 may be associated with poor prognosis across various tumor types." (PMID 41268439, 2025). "Additionally, analyses of 3 CRC spatial transcriptomics datasets revealed a high degree of spatial colocalization among SENP7, IL-10, and CD20, suggesting a potential spatial association between SENP7-expressing B cells and IL-10 production within the tumor microenvironment." (PMID 41362746, 2026). "The subcutaneous tumour model further demonstrated that adoptive transfer of B cells led to a marked reduction in tumour growth, whereas overexpression of SENP7 in B cells abrogated this effect." (PMID 41362746, 2026). "Immunohistochemistry results revealed that compared with CD20+ B cells in mice receiving NC-B cells, CD20+ B cells in the caecal orthotopic tumours of mice receiving adoptive transfer of SENP7-overexpressing B cells exhibited higher levels of IL-10 expression." (PMID 41362746, 2026). "For example, in prostate cancer, degradation of the deSUMOylase SENP7 promotes SUMOylation of HP1α, thereby inducing cellular senescence and exerting tumour-suppressive effects." (PMID 41362746, 2026). "Mechanistically, SPOP-mediated SENP7 downregulation increases the sumoylation levels of HP1α, leading to gene silencing and promoting cellular senescence, an important tumor suppression mechanism." (PMID 40521202, 2025). "Collectively, these results indicate that ENSR00000155786 and SENP7 function as potential tumor suppressor genes in CRC tumorigenesis and hold promise as therapeutic targets." (PMID 38863031, 2024). "Mechanistically, this variant exhibits an allele-specific effect in promoting transcription of both the eRNA ENSR00000155786 and mRNA SENP7, which synergistically suppress tumor cell proliferation." (PMID 38863031, 2024). "Mechanistically speaking, rs3094296 modulated the binding of TF HOXA5 in an allele-dependent manner to promote the expression of eRNA ENSR00000155786 and mRNA SENP7, which synergistically suppressed tumor cell proliferation." (PMID 38863031, 2024). "To explore SENP7-dependent transcriptional programs, we analyzed the gene expression profiles of tumor-infiltrating CD8+ T cells." (PMID 35143421, 2022). "To clarify the mechanism underlying the reduced antitumor activity of SENP7-deficient CD8+ T cells, we isolated tumor-infiltrating CD8+ T cells from tumor-bearing WT and KO mice for transcriptomic analysis." (PMID 35143421, 2022). "To delineate a potential interplay of both isopeptidases in tumor suppression, we first investigated the Senp7 expression level during murine B-cell lymphomagenesis in the Eμ-myc model." (PMID 35022408, 2022). "Collectively, these results indicate that ROS trigger SENP7 cytosolic translocation in tumor-infiltrating CD8+ T cells." (PMID 35143421, 2022). "We identify sentrin-specific protease 7 (SENP7) as a potential therapeutic target on B cells, where its inhibition restrains Breg differentiation and may represent a novel strategy to counteract tumour immune escape." (PMID 41362746, 2026).
tumor (continued). "In a prolonged subcutaneous tumour model (approximately 35 days), the inhibitory effect of anti-PD-1 monotherapy on tumour growth gradually decreased over time, whereas B-cell adoptive transfer restored tumour control, with further enhancement upon SENP7 knockdown in the transferred B cells." (PMID 41362746, 2026). "To determine whether the tumour-suppressive effect of SENP7 knockdown in B cells was mediated by CD8+ T cells, we employed a CD8+ T-cell depletion strategy involving the use of anti-CD8 antibodies in a murine model." (PMID 41362746, 2026). "Our results indicate that inhibiting SENP7 in B cells could serve as a promising strategy to render immunologically “cold” tumours more responsive to immune checkpoint inhibitors." (PMID 41362746, 2026). "ROS trigger cytosolic translocation of SENP7 in tumor-infiltrating CD8+ T cells." (PMID 35143421, 2022). "However, the tumor size and tumor-induced lethality were similar between the recipients of WT OT-II cells and KO OT-II cells, indicating that SENP7 is dispensable for CD4+ T cell antitumor function." (PMID 35143421, 2022). "Intriguingly, SENP7 was highly accumulated in tumor-infiltrating CD8+ T cells." (PMID 35143421, 2022). "Moreover, additional knockdown of SIRT1 in SENP7-overexpressing B cells suppressed tumour growth." (PMID 41362746, 2026). "We speculate that SENP7 might modulate the tumor-related immune and inflammatory responses." (PMID 28095500, 2017). "Sentrin-specific protease 7 (SENP7), a SUMO-specific protease, cleaves SUMO modifications from target proteins, thereby influencing their stability and functional activity in tumour cells." (PMID 41362746, 2026). "In both our and TCGA CRC patients, tumor tissues exhibited significant downregulation of ENSR00000155786 and SENP7 compared to normal tissues." (PMID 38863031, 2024). "Our findings reveal that SENP7, as an oxidative stress sensor, sustains CD8+ T cell metabolic fitness and effector functions and unveil an oxidative stress–sensing machinery in tumor-infiltrating CD8+ T cells." (PMID 35143421, 2022). "Similarly, ENSR00000155786 and SENP7 were found to be downregulated in both the TCGA dataset and our CRC tissues, exhibiting a synergistic effect on tumor cell proliferation." (PMID 38863031, 2024). "It further indicates that SENP7 may be involved in LLPS generation, which is restricted by SENP1, due to which a few dormant stem-like tumour cells resist acute hypoxia challenge." (PMID 36980166, 2023). "In response to NAC treatment, SENP7 in tumor-infiltrating CD8+ T cells did not localize to the cytoplasm." (PMID 35143421, 2022). "However, whether SENP7 senses oxidative stress to affect the phenotype and function of tumor-infiltrating CD8+ T cells has not previously been defined." (PMID 35143421, 2022).
cancer (6 papers, 2017 to 2025). A tumor composed of atypical neoplastic, often pleomorphic cells that invade other tissues. "Recent studies have shown that SPOP targets SENP7 for degradation during senescence, while cancer-associated SPOP mutants are impaired in this function." (PMID 40521202, 2025). "On the other hand, SENP7 has been described as a regulator of inflammation, and inflammation associates with cancer." (PMID 35887358, 2022). "Of note, the ubiquitin ligase cullin 3 adaptor SPOP, which appears frequently mutated in a variety of cancers, has been shown to promote senescence by targeting SENP7 for degradation, which results in HP1α increased sumoylation and, thereby, in epigenetic gene silencing." (PMID 35887358, 2022). "We have recently shown that, in cancer cells, SENP7 is downregulated under oxygen and glucose deprivation (OGD) conditions, which is a feature of inner cells inside solid tumors." (PMID 35887358, 2022). "These SUMOylation regulators have lower overall average mutation frequencies in 33 types of cancer, although SENP1, SENP5, SENP7, and PIAS3 regulators have higher mutation frequencies." (PMID 33123273, 2020). "Indeed, a number of SENP7 interactors, identified under inflammatory conditions, are cancer related proteins." (PMID 35887358, 2022). "Therefore, cancer cells may escape from harmful OGD conditions by upregulating SENP7, which emerges as a putative prognosis marker in CRC." (PMID 35887358, 2022). "This also correlated with the observation of prevalent amplification and deletion of the SENP7 and SENP3 genomic loci, respectively, in most cancer types." (PMID 35887358, 2022). "Rs4801778-T (PLEKHA4), rs11919389-C (ZBTB11), rs13050728-C (IFNAR2), and rs10774671-A (OAS1) exhibited a positive or negative regulation in TULP2, HSD17B14, LOC285359, LOC100009676, SENP7, IFNAR2, OAS3, and OAS1 in multiple cancer types." (PMID 35082790, 2021). "SENP7, a SUMO2/3-specific protease, plays a crucial role in various physiological and pathological processes, including epithelial-mesenchymal transition (EMT), cancer cell motility and invasiveness, DNA repair, and innate immune responses 206-209." (PMID 40521202, 2025).
inflammation (1 paper, 2022). Aberrant reaction of the microcirculation characterized by movement of fluid and leukocytes from the blood into extravascular tissues. "Knockdown of SENP7 or clearance of γδ T cells suppressed DSS-induced intestinal inflammation; upregulation of SENP7 expression was strongly statistically correlated with higher clinical disease indices in IBD patients." (PMID 36590401, 2022).
SENP7 also shares sentences with these, for which no sentence is quoted: malaria (8 papers); infection (2); arthrogryposis multiplex congenita (1); calculus (1); colitis (1); COVID-19 (1); epilepsy (1); glioblastoma (1); hematological diseases (1); hepatoma (1); immune diseases (1); Listeria monocytogenes infections (1); lung adenocarcinoma (1); Obesity (1); oral diseases (1); Parkinson’s (1); periodontal diseases (1); prostate carcinoma (1); respiratory failure (1); viral infection (1).